MEOX2 (mesenchyme homeobox 2)
Description:
Mesodermal transcription factor that plays a key role in somitogenesis and somitogenesis and limb muscle differentiation (By similarity). Required during limb development for normal appendicular muscle formation and for the normal regulation of myogenic genes (By similarity). May have a regulatory role when quiescent vascular smooth muscle cells reenter the cell cycle (By similarity). Also acts as a negative regulator of angiogenesis. Activates expression of CDKN1A and CDKN2A in endothelial cells, acting as a regulator of vascular cell proliferation. While it activates CDKN1A in a DNA-dependent manner, it activates CDKN2A in a DNA-independent manner. Together with TCF15, regulates transcription in heart endothelial cells to regulate fatty acid transport across heart endothelial cells (By similarity).
Synonyms: GAX; MOX2
Tractability: No criterion of Open Targets' tractability assessment is met for any kind of drug.
Gene: Protein-coding gene on chromosome 7 (15,611,211 to 15,686,818, reverse strand). Ensembl gene ENSG00000106511.
Subcellular location: Nucleus; Nucleus speckle
Gene Ontology:
Molecular function: DNA-binding transcription activator activity, RNA polymerase II-specific; DNA-binding transcription factor activity; protein binding; RNA polymerase II cis-regulatory region sequence-specific DNA binding; sequence-specific DNA binding; sequence-specific double-stranded DNA binding; DNA-binding transcription factor activity, RNA polymerase II-specific; DNA binding
Biological process: negative regulation of cell migration involved in sprouting angiogenesis; positive regulation of transcription by RNA polymerase II; regulation of transcription by RNA polymerase II; somite development; regulation of DNA-templated transcription
Cellular component: cytoplasm; nuclear speck; nucleus; chromatin
Genetic constraint (gnomAD): Loss-of-function variants: 11 observed, 24.07 expected, observed/expected ratio (o/e) 0.46, 90% interval 0.29 to 0.76. The upper end of that interval is the gene's LOEUF score, 0.76, which puts it in group 3 of 6, group 1 being the genes least tolerant of losing a copy. Missense variants: 436 observed, 389.99 expected, observed/expected ratio (o/e) 1.12, 90% interval 1.03 to 1.21. Synonymous variants: 189 observed, 155.24 expected, observed/expected ratio (o/e) 1.22, 90% interval 1.08 to 1.37.
Homologues: Orthologues: dog MEOX2 (99% identical), macaque MEOX2 (99% identical), chimpanzee MEOX2 (99% identical), pig MEOX2 (99% identical), rabbit MEOX2 (99% identical), mouse Meox2 (98% identical), rat Meox2 (98% identical), guinea pig MEOX2 (97% identical), tropical clawed frog meox2 (85% identical), zebrafish meox2a (67% identical), Drosophila melanogaster btn (22% identical). Paralogues in human: MEOX1 (40% identical).
Diseases named in the same sentence as MEOX2 in open-access papers:
MEOX2 is named in the same sentence as 61 diseases in open-access papers, as found by Europe PMC text mining. Sharing a sentence is not in itself a finding about the gene and the disease. The quoted sentences say what the papers report.
glioma (18 papers, 2019 to 2026). A benign or malignant brain and spinal cord tumor that arises from glial cells (astrocytes, oligodendrocytes, ependymal cells). "The MEOX2 gene is located at the 7p21 locus and its overexpression in gliomas is associated with chromosome 7 gains, a hallmark alteration in classical subtype GBMs." (PMID 37568909, 2023). "To get insight into the molecular mechanism underlying MEOX2 mediated glioma malignant phenotype, we analyzed the enriched pathways of genes that positively associated with MEOX2 expression in TCGA, CGGA datasets." (PMID 35436995, 2022). "Consistently, MEOX2 causes glioma tumor development in mice and greatly lowers the survival period of tumor-bearing mice." (PMID 35436995, 2022). "The high expression of MEOX2 transcription factor is closely associated with poor overall survival in glioma." (PMID 34885053, 2021). "MEOX2, which encodes a protein involved in glioma development and angiogenesis, has expression levels that may correlate with tumor invasiveness and vascularization." (PMID 40535771, 2025). "MEOX2 expression was shown to be inversely linked with the prognosis of glioma patients." (PMID 35436995, 2022). "Interestingly, it is reported that only IDH1/2 wild-type gliomas (59% GBMs and 41% LGGs) highly expressed MEOX2 compared with IDH1/2-mutated gliomas in TCGA dataset." (PMID 35646656, 2022). "In the discovery process, two particular genes stand out with high hazard ratio (HR) and concordance index (CI) in univariate Cox model, AQP1 (HR = 3.3, p < 0.05, CI = 0.711) and MEOX2 (HR=2.5, p < 0.05, CI = 0.675), both of which are lesser known to be associated with survival in gliomas." (PMID 30626092, 2019). "We also provide an evidence that the expression levels of SNAI and MEOX2 are significantly associated with histopathological grade and survival time in glioma patients, indicating that these two transcriptional factors play a crucial role in the malignancy of glioma." (PMID 31632439, 2019). "In addition, the transcription factor MEOX2 is closely associated with overall survival in glioma." (PMID 37501725, 2023). "Ubiquitous activation of mutant Ppm1d was modeled using the Meox2-Cre driver, and primary gliomas were modeled using the RCAS/tv-a system to introduce Cre and PDGFB co-drivers into Nestin-positive neural stem cells." (PMID 41394550, 2025). "Specifically, previous studies described the ability of several molecular markers involved for predicting the prognosis of glioma and these molecular markers include MEOX2, PDIA5, and DDX3X." (PMID 39012280, 2024). "It has been demonstrated that MEOX2 expression level is correlated with its methylation status in glioma samples and that downregulation of MEOX2 leads to increased viability in glioma stem cells through modulation of the ERK/MAPK pathway." (PMID 38468866, 2024). "Our findings indicate that MEOX2 promotes tumorigenesis and progression of glioma partially through the regulation of CTSS." (PMID 35436995, 2022). "One of the important findings of this study is that silencing MEOX2 in glioma cells resulted in inhibition of cell motility." (PMID 35436995, 2022). "To understand the prognostic value of MEOX2 in gliomas, we analyzed MEOX2 expression in public databases." (PMID 35436995, 2022). "Previous studies documented that MEOX2 existed a dual role in human cancers, however, was determined an overexpression status in glioma." (PMID 35436995, 2022). "Wound-healing and transwell assay verified that MEOX2 overexpression enhanced the invasion and migration abilities of glioma cells." (PMID 35436995, 2022). "Collectively, these data indicate that MEOX2 overexpression evidently promoted glioma cell proliferation in vitro and in vivo, as well as contributed to cell motility." (PMID 35436995, 2022).
glioma (continued). "MEOX2 is a homeodomain-containing transcription factor whose expression is extremely enriched in gliomas compared to all other types of tumors and was very recently found to be highly expressed in GSCs as well." (PMID 35565433, 2022). "Attractively, recent publications described MEOX2 significantly upregulation in glioma and predicted MEOX2 as a prognostic biomarker of glioma." (PMID 35436995, 2022). "Immunofluorescence images of vimentin revealed that silencing MEOX2 resulted in significant downregulation of vimentin in glioma cells." (PMID 35436995, 2022). "Further study found that depletion of MEOX2 inhibited glioma cell proliferation by arresting cell cycle at G2/M phase, however, not that of cell apoptosis." (PMID 35436995, 2022). "Bioinformatic analyses of public databases and investigation of MEOX2 expression in patients with glioma demonstrated that MEOX2 was abundant at both mRNA and protein levels in glioma." (PMID 35436995, 2022). "To confirm the role of CTSS in MEOX2 inducing glioma malignant phenotype, we constructed stable cell lines by transfected CTSS overexpression lentiviruses into shMEOX2 cells for the rescue assay." (PMID 35436995, 2022). "The level of phosphorylated FAK(Y925) was significantly decreased in MEOX2 silenced glioma cells, while increasing in MEOX2 overexpression cells." (PMID 35436995, 2022). "CCK-8 and EdU assay verified that silencing MEOX2 significantly attenuated the proliferation of glioma cells." (PMID 35436995, 2022). "Then, both loss-of-function and gain-of-function studies were performed in glioma cell lines and glioma stem cells, confirmed that MEOX2 facilitated cell proliferation of glioma in vitro and in vivo." (PMID 35436995, 2022). "GSC23 shMEOX2 cells were injected intracerebrally to evaluate the impact of MEOX2 on glioma cells growth in vivo, and the tumor size demonstrated that the growth of MEOX2-depleted cells was suppressed." (PMID 35436995, 2022). "To investigate the role of MEOX2 in glioma cells, we constructed MEOX2-silenced cell models by transfected siRNAs into SNB19, U118, GSC23 cells." (PMID 35436995, 2022). "GSEA results showed that epithelial-mesenchymal transition (EMT) and focal adhesion were the most significant correlation with MEOX2 expression in glioma." (PMID 35436995, 2022). "Further, we found that CTSS, which is transcriptionally regulated by MEOX2, contributed to cell proliferation and motility in glioma." (PMID 35436995, 2022). "Further, we performed wound-healing and transwell assay to examine cell motility, and found that silencing MEOX2 in glioma cells resulted in inhibition of cell migration and invasion." (PMID 35436995, 2022). "Collectively, these data demonstrated that what the role of CTSS in aggressive behavior and its molecular mechanism in glioma cells is similar to MEOX2, also indicated that MEOX2 contributed to the malignant behavior of glioma by CTSS activation." (PMID 35436995, 2022). "Bioinformatics analysis of available public databases suggested that MEOX2 is overexpressed in gliomas and correlates with the poor prognosis of patients." (PMID 35436995, 2022). "Our results demonstrated that MEOX2 was upregulated in glioma, particularly in GBM, and it is significantly positively correlated with the prognosis of glioma patients; suggesting that MEOX2 has the potential to be prognostic markers for glioma." (PMID 35436995, 2022). "Immunohistochemistry (IHC) results also revealed that MEOX2 was increased with increasing WHO grades in glioma, and higher than NBT." (PMID 35436995, 2022). "We analyzed different types of MEOX2 genetic alterations in glioma, and found that MEOX2 harbored a large gain or amplification genetically." (PMID 35436995, 2022). "Together, these results suggest that MEOX2 knockdown significantly inhibited glioma cell proliferation in vitro and in vivo, and also suppressed cell motility." (PMID 35436995, 2022).
glioma (continued). "In our study, we confirmed that MEOX2-CTSS axis regulated glioma cell growth and motility through intracellular mechanisms." (PMID 35436995, 2022). "Together, these data confirmed that CTSS acts as a direct target gene of MEOX2 and is positively regulated by MEOX2 in glioma cells." (PMID 35436995, 2022). "MEOX2 has recently been described as an interesting prognostic biomarker, especially for lower grade glioma." (PMID 34885053, 2021). "We have previously shown that in glioma, there was an inverse correlation between MEOX2 expression and its promoter methylation status." (PMID 34885053, 2021). "Our team recently demonstrated that MEOX2 was a potent prognostic factor of patient outcome in all gliomas and, more interestingly, in lower grade glioma." (PMID 34885053, 2021). "We previously demonstrated that the transcription factor MEOX2 was a robust prognostic factor, which correlated with overall survival and progression-free survival in patients with glioma." (PMID 34885053, 2021). "Little is known about MEOX2 contribution to carcinogenesis and this study constitutes the first attempt to characterize the functional role of MEOX2 in glioma, and specifically, in GSC." (PMID 34885053, 2021). "The literature on MEOX2 in glioblastomas is scarce; however, there are data that indicate that MEOX2 functions as a transcription factor involved in the regulation of viability, proliferation, and differentiation of glioma cells by interacting with PI3K/Akt and MAPK pathways." (PMID 37568909, 2023). "HE images revealed that MEOX2-overexpressed glioma cells induced a bigger intracerebral tumor." (PMID 35436995, 2022). "Additionally, we observed that MEOX2 expression was higher in most glioma cells (U118, U251, SNB19, LN229, GSC23) than NHA." (PMID 35436995, 2022). "Here, we demonstrated that E-cadherin was significantly augmented while N-cadherin, vimentin, and p-FAK/FAK ratio was reduced in glioma cells with MEOX2 knockdown, and the expression of these molecules showed the opposite trend in MEOX2 overexpression glioma cells." (PMID 35436995, 2022). "Importantly, RNA-sequencing, ChIP-qPCR assay, and luciferase reporter assay revealed Cathepsin S (CTSS) as a novel transcriptional target of MEOX2 in glioma cells." (PMID 35436995, 2022). "Thus, we will further explore the roles and molecular mechanisms of MEOX2 in glioma, and provide insight into novel therapeutic strategies for glioma." (PMID 35436995, 2022). "Moreover, MEOX2-depleted induced inhibition of glioma cells migration and invasion were partially restored by re-expression of CTSS." (PMID 35436995, 2022). "Therefore, validation of the mechanism of the MEOX2 isoform in glioma warrants further investigation." (PMID 35436995, 2022). "Therefore, phalloidin staining measured cytoskeletal actin filament in MEOX2-silenced glioma cells, and the actin filaments displayed a broken and sparse status." (PMID 35436995, 2022). "PI3K/AKT, Wnt/β-catenin, Hippo pathways are closely related with EMT and focal adhesion in glioma, thus the mechanism of MEOX2 in glioma might be more complicated than this study presents." (PMID 35436995, 2022). "Here, we report that MEOX2 functions as a tumor-initiating element in glioma." (PMID 35436995, 2022). "MEOX2 was increased in gliomas with higher WHO grade in TCGA, CGGA, Rembrandt databases." (PMID 35436995, 2022). "In conclusion, in the present study, we demonstrated that transcription factor MEOX2 could serve as a poor prognostic indicator in glioma, and MEOX2-CTSS axis contributes to the malignant progression of glioma by regulation of EMT and focal adhesion." (PMID 35436995, 2022). "In our study, Cathepsin S (CTSS) was identified as a major downstream target gene of MEOX2 in glioma by RNA-sequencing, although, other target genes may be also regulated via MEOX2." (PMID 35436995, 2022). "In our study, we confirmed that glioma had gain and amplification on the MEOX2 locus, which may upregulate MEOX2 expression." (PMID 35436995, 2022).
glioma (continued). "In this study, we demonstrated that MEOX2 contributes to cell proliferation and motility in glioma." (PMID 35436995, 2022). "Further, we investigated the effects of MEOX2-CTSS axis in glioma tumorigenesis in vivo." (PMID 35436995, 2022). "In addition, two lesser known genes, AQP1 and MEOX2, are discovered to be prognostic to gliomas patients overall survival through the deep learning approach." (PMID 30626092, 2019). "Targeting MEOX2-CTSS axis might be a promising alternative for the treatment of glioma." (PMID 35436995, 2022). "Compared to glioses, glial neoplasms were significantly more often positive (p < 0.001, χ2) for EGFR (33.8%), MEOX2 (48.9%), SOX11 (69.9%) and INSM1 (64.9%)." (PMID 37568909, 2023). "After excluding IDH1 R132H mutant gliomas from the analysis, the specificity increased to 41.5% for EGFR, 53.2% for MEOX2, 50.7% for SOX11 and 57.3% for INSM1." (PMID 37568909, 2023). "The top five TFs with the highest correlations in both datasets consisted of STAT1, MEOX2, CREM, NR2F2, and IRF3, indicating that they were likely to regulate the expression of SERPINF1 in glioma." (PMID 36980858, 2023). "We postulated that immunohistochemical detection of proteins expressed preferentially in gliomas (EGFR, MEOX2, CD34) or during embryonal development (SOX11, INSM1) can be used to distinguish reactive gliosis from glioma." (PMID 37568909, 2023). "Glial neoplasms were significantly more often (p < 0.001, χ2) positive for EGFR (34.1% vs. 0%), MEOX2 (49.3% vs. 2.3%), SOX11 (70.5% vs. 20.4%), and INSM1 (65.4% vs. 2.3%)." (PMID 37568909, 2023). "The results indicated that IBSP, MEOX2, and EPHB1 were inclined to express highly in glioma tissues compared with the adjacent relatively normal tissues, while the expression of NOG and GFRA1 tended to decrease in glioma tissues." (PMID 37501725, 2023). "Next, immunoblotting verified that silencing MEOX2 significantly suppressed CTSS protein expression, and overexpression of MEOX2 resulted in CTSS upregulation in glioma cells." (PMID 35436995, 2022). "Immunoblotting and RT-PCR analysis results showed that mRNA and protein levels of MEOX2 in fresh glioma tissues were significantly higher than it’s in NBT, especially in Grade3, 4 gliomas." (PMID 35436995, 2022). "CCK-8 and EdU assay showed that rescue of CTSS partially restored the viability of MEOX2-silenced glioma cells, and limiting dilution assay revealed that rescue of CTSS also partially restored the self-renewal capacity of MEOX2-depleted GSC23 cells." (PMID 35436995, 2022). "We analyzed the expression data of MEOX2 and CTSS in TCGA dataset, CTSS expression was found to be closely correlated with MEOX2 in glioma." (PMID 35436995, 2022). "Our findings indicate that MEOX2-CTSS axis has the potential to be prognostic markers and therapeutic targets for glioma." (PMID 35436995, 2022). "Gene expression analysis of glioma and glioblastoma cells revealed that Meis2 was one of the differentially expressed genes and it could be a prognostic biomarker for glioma and glioblastoma development, in addition to with other genes, including Meox2, Pitx2, Nr2e1, and Tfap2B." (PMID 33402862, 2020). "In comparison to other glioma subtypes, the GS2 exhibited higher expression levels of IBSP, PLA2G2A, NNMT, CA9, and MMP9, while the GS5 showed higher expression levels of CHI3L1, IGFBP2, EMILIN3, MEOX2, and PDPN." (PMID 38332637, 2024). "Glioma and GBM patients with high MEOX2 expression possessed a poorer prognosis." (PMID 35436995, 2022). "Therefore, MEOX2-CTSS axis has the potential to be prognostic markers and therapeutic targets for glioma." (PMID 35436995, 2022). "Therefore, our findings suggested that MEOX2 was a crucial effector molecule that induced EMT, formation of focal adhesion, and F-actin polymerization to mediate cell motility in glioma." (PMID 35436995, 2022).
glioma (continued). "In summary, these results suggest that MEOX2 may regulate the EMT process, formation of focal adhesion, and F-actin assembly in glioma cells." (PMID 35436995, 2022). "GSEA analysis indicated that MEOX2 may involve in the process of EMT and focal adhesion in glioma cells, which are the important mechanisms that participate in glioma invasion and migration." (PMID 35436995, 2022). "In addition, inhibition of MEOX2 impaired cell growth and motility in glioma, while CTSS expression rescue did not entirely restore behavior, implying the presence of other cellular or molecular mechanism." (PMID 35436995, 2022). "MEOX2 has never been studied in glioma stem-like cells (GSC), responsible for glioma recurrence." (PMID 34885053, 2021).